CCL26 (C-C motif chemokine ligand 26)
Diseases named in the same sentence as CCL26 in open-access papers (continued):
Sharing a sentence is not in itself a finding about the gene and the disease.
cancer (24 papers, 2015 to 2025). A tumor composed of atypical neoplastic, often pleomorphic cells that invade other tissues. "It was reported that CCL26 is regulating expression of cancer-associated genes during airway inflammation." (PMID 32154227, 2020). "Previous studies have linked high CCL26 expression with poor prognosis across several cancers." (PMID 39931245, 2025). "Besides, the mRNA expression level of CCL26 in cancer cells was positively linked to the proportions of PMN-MDSCs, while no such correlation was observed with M-MDSCs." (PMID 41280721, 2025). "In the scRNA-seq dataset of stomach carcinogenesis, CCL26 exhibited a significant up-regulation trend in cancer cells, with its expression levels positively correlating with disease progression." (PMID 41280721, 2025). "CCL26 levels in different cancer and normal tissues were analyzed and validated in 67 OSCC patients through immunohistochemical staining (IHC)." (PMID 39931245, 2025). "While previous studies have touched upon the role of CCL26 in specific cancers, our investigation is the first to explore it in OSCC." (PMID 39931245, 2025). "In terms of localization, CCL26 was primarily expressed in stomach glands (epithelial cells), aligning with the up-regulation of CCL26 observed in cancer cells in our previous scRNA-seq analysis, whereas PMN-MDSCs preferentially infiltrated stromal areas." (PMID 41280721, 2025). "Eotaxins (specifically CCL24 and CCL26) have also been correlated to cancer development through M2 macrophage polarization, angiogenesis, invasion and migration, and recruitment of eosinophils." (PMID 39198407, 2024). "In contrast, in preinvasive lesions and in calbindin-expressing LUSC tumors, these chemokines are produced predominantly by myeloid cells themselves, with cancer cells expressing only the monocyte chemoattractant CCL26." (PMID 37192000, 2023). "Since elevated CCL26 appears to be a generalized finding in a broad range of cancer stroma, we explored its role further." (PMID 36045118, 2022). "Using HCC as a model, we previously demonstrated hypoxia as a central driver for MDSC accumulation in tumors and showed that hypoxic cancer cells secreted CCL26 to attract MDSCs33." (PMID 28894087, 2017). "These variations suggest that CCL26’s biological role and impact on survival differ among cancers." (PMID 39931245, 2025). "However, we were most intrigued by our CCL11 and CCL26 results because both of these chemokines are involved in promoting macrophage polarization and cancer metastasis." (PMID 38554160, 2024). "In addition, we found that TAB182 depletion upregulated genes significantly associated with the positive regulation of actin filament polymerization, such as CCL24 and CCL26, which play essential roles in cancer cell invasion and migration." (PMID 37953246, 2023). "However, it has also been reported that in malignant tumors, invasion and metastasis are promoted by signaling via CCL26 or CCR36–8." (PMID 34518591, 2021). "While previous studies have offered preliminary insights into the role of CCL26 in specific cancers, targeting chemokines and their receptors has been proposed as a promising strategy for immunotherapy, its broader implications in the realm of immunotherapy across OSCC remain unknown." (PMID 39931245, 2025). "Seven chemokines (CCL18, CCL8, CXCL9, CXCL10, CXCL11, CCL26, and CCL7) showed positive relations in more than 25 cancer types." (PMID 38655053, 2024). "Validation of these data exhibited that chemokines involved in promoting macrophage polarization and cancer metastasis, including CCL11 and CCL26, were stimulated by Wnt3a signaling and their expression was abrogated by treatment with rSFRP1." (PMID 38554160, 2024). "In particular, chemokines, including CXCL8, CXCL10, CXCL11, CXCL16, CCL26, and CCL7, as well as chemokine receptors, including CXCR3, CCR2, CCR5, and CCR1, were positively correlated with MRPL13 expression in various cancer types." (PMID 37827692, 2023).
cancer (continued). "Mo-MDSC recruitment by the two chemokines takes place mainly during hypoxia, when the expression of eotaxin-3/CCL26 and CX3CL1 increases in cancer cells." (PMID 32466280, 2020). "Moreover, expression of CALB1 in cancer cells exhibited a highly significant inverse correlation with cancer cell–intrinsic expression of CXCL1, CXCL2, and CXCL8 and a positive correlation with CCL26 expression, which did not, however, reach statistical significance (P = 0.057)." (PMID 37192000, 2023).
infection (22 papers, 2016 to 2025). The state of being infected such as from the introduction of a foreign agent such as serum, vaccine, antigenic substance or organism. "Serpin peptidase inhibitor 3 (SPIA3), alpha-2-macroglobulin-like 4 (A2ML4), complement component 4 binding protein (LOC419851) and chemokine (CCL26) showed the highest increase in response to the infection." (PMID 40275387, 2025). "In agreement, no cytokines or chemokines were found to be significantly regulated at the transcriptional level and two proteins related to recruitment and activation of immune cells were less abundant post infection compared to controls (CCL26 and IL13)." (PMID 39247193, 2024). "When looking at the effects of infection on expression of immune-related genes in the proximal colon we found an upregulation of genes related to type-2 responses such as CCL26, CCR4, and RETNLB (fold changes 1.4, 1.5 and 1.4, respectively)." (PMID 38081984, 2023). "Our study is the first to report on difference in TLR5, CXCL17, CCL26, IL1RL2, or IL3RA levels in sexes during infection." (PMID 36171541, 2022). "Infection with O. dentatum significantly increased expression of IL4, IL13, ARG1, CCL17 and CCL26, with a concurrent trend for down-regulation of the expression of Th1-related genes such as IL8." (PMID 35069576, 2021). "In conclusion, these data provide important mechanistic information regarding the nutritional role of vitamin A in infection and inflammation suggested from the co-induction of the M2a markers CCL13 and CCL26 along with the M2c marker IL-10." (PMID 32431691, 2020). "Additionally, five genes (CCL26, MIR8485, ULBP1, CCL13, CISH) and one unannotated gene (ENSG00000289505) were downregulated in the transwell relative to the other infection groups." (PMID 40630957, 2025). "HRV-16 (MOI = 1) infection induced both TSLP and CCL26 mRNA and protein expression in NHBE cells." (PMID 32120846, 2020). "We did not observe basophils or eosinophils histologically during infection with C. violaceum, and this was again supported by the absence or low expression of chemokines involved in trafficking of these cell types (i.e. Ccl11, Ccl24, and Ccl26)." (PMID 38352492, 2024). "In particular, the expression of IL13 and RETNLB was significantly increased in infected pigs, regardless of diet (main effect of infection with a fold change of 3.7 and 1.7, respectively), and the expression of CCL26, IL10 and TFF2 also tended to be increased." (PMID 38081984, 2023). "On the other hand, there was no distinct trend between infection with CVI988 and vvRB1B and the expression of cytokines and chemokines, such as IL-10, IFN-γ, STAT1, IRF1, CCL19, and CCL26." (PMID 32210095, 2020).
inflammation (6 papers, 2011 to 2024). Aberrant reaction of the microcirculation characterized by movement of fluid and leukocytes from the blood into extravascular tissues. "Previous findings have demonstrated the critical role of CCL26 and periostin in regulating eosinophilic inflammation." (PMID 39361432, 2024). "The role of SERPINB10 in allergic airway eosinophilic inflammation is thought to be elicited via modulation of periostin and CCL26 (chemokine (C-C motif) ligand 26) expression." (PMID 34198546, 2021). "Eosinophil: granular leukocytes that are recruited to the lung by IL-5 and C-C chemokines (CCL11, CCL24 and CCL26) to mediate allergen-induced airway inflammation." (PMID 23828644, 2013).
bacterial infection (2 papers, 2021 to 2024). "Similar to Vero, a number of cytokines associated with bacteria were identified in Huh7 cells, such as lipocalin 2 (LCN2), which inhibits bacterial infection, was upregulated, whereas C-C motif chemokine ligand 26 (CCL26), a chemoattractant for eosinophils and basophils, was downregulated." (PMID 34899651, 2021). "Eosinophil-attracting chemokines such as eotaxin-1/CCL11, eotaxin-2/CCL24, and eotaxin-3/CCL26 promote host immunity against parasitic and bacterial infection." (PMID 39502090, 2024).
infectious disease (1 paper, 2017). A disorder directly resulting from the presence and activity of a microbial, viral, or parasitic agent in humans. "Several inflammatory conditions and infectious diseases also comprise the selective eosinophil chemotaxis and transendothelial migration mediated by the CC-chemokines eotaxin-1, eotaxin-2 and eotaxin-3 (CCL11, CCL24, and CCL26, respectively) via the eotaxin receptor CCR3." (PMID 29322036, 2017).
CCL26 also shares sentences with these, for which no sentence is quoted: Obesity (5 papers); eosinophilic disorders (3); dementia (2); esophageal cancer (2); fibrosis (2); food allergy (2); gastroesophageal reflux (2); polyp (2); respiratory disease (2); alopecia areata (1); Alzheimer disease (1); amyloid (1); carcinoma in situ (1); celiac disease (1); cholangiocarcinoma (1); cholera (1); chronic obstructive pulmonary disease (1); chronic rhinosinusitis with nasal polyps (1); ciliopathies (1); Cirrhosis (1); colitis (1); corneal ulcer (1); Crohn disease (1); diabetes (1); diabetic eye disease (1); differentiated thyroid carcinoma (1); Down syndrome (1); eating disorder (1); endometriosis (1); eosinophilic granulomatosis with polyangiitis (1).
A further 28 diseases each share a sentence with CCL26 in 1 paper.